SIRT1 (sirtuin 1)
Diseases named in the same sentence as SIRT1 in open-access papers (continued):
Sharing a sentence is not in itself a finding about the gene and the disease.
kidney diseases (continued). "Sirt1 has recently been found to act as an important regulator of immune cells and immune responses, which deserves the attention of researchers studying kidney diseases." (PMID 36052119, 2022). "The role of SIRT1 in kidney diseases has been focused in recent years." (PMID 33867828, 2021). "Endothelial SIRT1 depletion or SIRT1 inactivation frequently accompanies many renal diseases." (PMID 32802201, 2020). "In a kidney disease model, Sirt1 activation attenuates cisplatin-induced renal tubular injury." (PMID 30401006, 2018). "Sirt1 is a key molecule that regulates renal protective effects in various renal disorder models." (PMID 30401006, 2018). "As the cellular and molecular mechanisms of SIRT1 has been recently reviewed, as well as the role and mechanism of other sirtuins in kidney disease, this review is focused primarily on its modulation of transcription factor through deacetylation in the setting of DKD." (PMID 30386303, 2018). "It has been reported that expression and activation of SIRT1 are downregulated in inflammation and fibrosis in liver and kidney diseases and resveratrol could activate SIRT1 and thus ameliorate inflammation and fibrosis." (PMID 28698801, 2017). "The renal protected effects of SIRT1 have been demonstrated in various kidney diseases." (PMID 28425936, 2017). "Considering the previously reported role of SIRT1 in kidney disease, it may become a new therapeutic target of kidney disease including DN." (PMID 25386563, 2014). "Therefore, modifying the expression of SIRT1 through miR-200a-3p modulation could serve as a potential therapeutic target to promote renoprotection in HTN and DM-associated renal disease." (PMID 40723868, 2025). "SIRT1 could delay the progression of various kidney diseases by inhibiting apoptosis and fibrosis." (PMID 35721758, 2022). "The Sirt1/eNOS pathway may be a common therapeutic target for renal disease." (PMID 34439446, 2021). "However, beneficial effect of Sirt1 activation has not been reported in association with its deacetylation targeting HIF‐1α in the kidney disease." (PMID 30614190, 2019). "Therefore, our data suggest that inducing SIRT1, HO-1, and thioredoxin may have clinical therapeutic potential in kidney diseases under excessive ER stress conditions." (PMID 28146117, 2017). "Therefore, H2S may modulate liver and renal lipid metabolism through an enhanced SIRT1 signal and contribute to the prevention of renal disease progression." (PMID 27882191, 2016). "Thus, 24 h of fasting or short-term CR could potentially be applied to renal disease models to explore the roles of increased Sirt1 in renoprotection." (PMID 27600292, 2016). "Collectively, these findings suggest that Sirt1's deacetylase activity decreases in nutrient excess conditions, and its activation, which acts as a calorie restriction mimetic, may be a new therapy for renal disease in obese and diabetic patients." (PMID 25126552, 2014). "In addition to scavenging ROS, resveratrol may have numerous protective effects against age-related disorders, including renal diseases, through the activation of SIRT1." (PMID 24379901, 2013). "For example, it has been found that polydatin promotes mitochondrial biogenesis and protects against mitochondrial oxidative stress via the activation of Sirtuin-1-PGC-1α pathway and Sirtuin-1-Nrf2-ARE pathway in kidney diseases." (PMID 37007023, 2023). "The potential of polyphenols to restore SIRT1 and NAD+ metabolism in kidney diseases has received significant attention." (PMID 37635982, 2023). "Therefore, SIRT1 might be a therapeutic agent for the treatment of renal disorders." (PMID 35137552, 2022). "Here, we summarize the roles of SIRT1 and NAD+ metabolism in renal pathophysiology and provide an overview of polyphenols that have the potential to restore SIRT1 and NAD+ metabolism in renal diseases." (PMID 35277012, 2022).
kidney diseases (continued). "SIRT1, a NAD(+)-dependent deacetylase, regulates a broad range of pathogeneses of many chronic diseases, including metabolic and renal diseases." (PMID 35888719, 2022). "In this article, we review the protective effects of SIRT1 and NAD+ metabolism on renal function because these effects have been recently described based on several models of renal disorders with metabolic impairment." (PMID 35277012, 2022). "As a class of small single-stranded noncoding RNA, miR-34a is involved in the pathological process of various diseases such as dietetic kidney disease by regulating the function of target genes such as Egr1, GAS1, and Sirt1/HIF-1α." (PMID 36345369, 2022). "Silent information regulator 1 (SIRT1), a nicotinamide adenine dinucleotide- (NAD+-) dependent deacetylase, plays an important role in the pathophysiology of kidney disease." (PMID 33880382, 2021). "Recently we showed that the podocyte-specific overexpression of SIRT1 attenuated proteinuria and kidney injury in an experimental model of DKD, further confirming SIRT1 as a potential target to treat kidney disease." (PMID 30386303, 2018). "SIRT1, an NAD+-dependent deacetylase, plays a protective role in kidney disease." (PMID 37635982, 2023). "In addition, we provide an overview of the polyphenols that have the potential to restore SIRT1 and NAD+ metabolism in renal diseases." (PMID 35277012, 2022). "Although Sirtuin-1 activators such as resveratrol have been demonstrated to successfully treat kidney injury in animal models, there have been no clinical trials to assess Sirtuin-1 activators for patients with kidney diseases." (PMID 33158122, 2020). "Concerning miR-200a, its involvement in renal diseases through SIRT1 regulation has not been reported to date." (PMID 32887498, 2020). "Furthermore, sodium isosteviol has the potential to ameliorate high‐fat/high‐cholesterol‐induced kidney disorders, myocardial dysfunction, and nonalcoholic fatty liver disease (NAFLD) through the activation of the Sirtuin 1 (Sirt1)/AMPK signaling pathway and the suppression of inflammation." (PMID 39898123, 2025). "Although evidence from clinical settings is scarce, preclinical studies have suggested that resveratrol may have a protective effect against renal diseases, through attenuation of oxidative stress and the activation of NAD-dependent deacetylase sirtuin-1 (SIRT1), as reviewed elsewhere." (PMID 33266114, 2020). "Similarly, reduction in SIRT1 expression was observed in kidney glomeruli and tubulointerstitial compartments of patients with mild to severe DKD, which was inversely correlated with the histopathological severity of the renal disease and with the amount of proteinuria." (PMID 25346724, 2014).
neurological disorders (54 papers, 2010 to 2024). "There is evidence that SIRT1 is important in the prevention of many neurological disorders, and a possible mechanism is associated with oxidative stress, energy metabolism, mitochondrial function and autophagy." (PMID 38794753, 2024). "It has been demonstrated that SIRT1 is implicated in the modulation of immune response and could reduce neuroinflammation in a variety of neurological disorders." (PMID 34899720, 2021). "As such, upregulation of SIRT1 has emerged as a potential therapeutic target for the treatment of neurological disorders and cognitive impairment in the brain." (PMID 38671843, 2024). "In the brain, SIRT1 is highly expressed in neurons and exerts an endogenous neuroprotection in a variety of neurological disorders." (PMID 35693703, 2022). "Recent studies have suggested that Sirtuin-1 (SIRT1) plays a critical role in several different neurological disorders via its involvement in microglial activation." (PMID 36437988, 2022). "Previous studies showed that activation of SIRT1 reversed nerve damage in different neurological diseases by augmenting hippocampal neurogenesis." (PMID 34221003, 2021). "As the main regulator of neurological diseases, SIRT1 plays a protective role in neurological diseases by regulating inflammation, oxidative stress, and cell apoptosis." (PMID 34956378, 2021). "SIRT1 has been shown to have beneficial effects on brain injury, ischemic injury, and other neurological diseases." (PMID 34616305, 2021). "Previous studies have reported that SIRT1 participates in regulating immune responses and inducing M2 microglia in a variety of neurological disorders." (PMID 34899720, 2021). "The function of SIRT1 is increasingly recognized as especially important in the pathogenesis of neurological diseases." (PMID 34899720, 2021). "Sirt1 is involved in numerous biological and pathophysiological processes and has recently been considered as an emerging neuronal therapeutic target for neurological diseases." (PMID 34959841, 2021). "SIRT1 is the main regulator of neurogenesis and plays a neuroprotective role in neurological diseases." (PMID 34221003, 2021). "Sirt1 is predominantly expressed in neurons and has been reported to be involved in neurological disorders, including neuropathic pain." (PMID 32089065, 2020). "The regulation of the circadian genes by SIRT1 in the central clock has also been reported to be disrupted in a number of neurological diseases." (PMID 30532738, 2018). "We also discuss the potential benefits of SIRT1 activators in the animal models of neurological diseases." (PMID 30416425, 2018). "SIRT1 has been the most extensively studied, and accumulating evidence suggests that SIRT1 plays a protective role in normal brain physiology and neurological disorders." (PMID 26732053, 2016). "Our PrP-Sirt1 mice with minimal neurological deficits are suitable for testing the effects of SIRT1 supplementation on various models of neurological disorders." (PMID 25167838, 2014). "Neuroprotective activity of various SIRT1 activators have been reported in rodent models of neurological disorders, which could be tested in patients with neurological disorders." (PMID 38416341, 2024). "As a result, SIRT1 has been identified as a potential therapeutic target for neurological diseases." (PMID 37892107, 2023). "Both protective and detrimental effects of SIRT1 in neurological diseases have been reported." (PMID 34650436, 2021). "Specifically, our findings highlight a mechanism by which GJD may prevent neurological diseases by activating the Sirt1 signaling pathway." (PMID 34959841, 2021). "SIRT1 (silent mating type information regulation 2 homolog), a known nicotinamide adenine dinucleotide (NAD)-dependent deacetylase, is present ubiquitously in the brain, and several studies have demonstrated a protective role of SIRT1 in various neurological disorders including SAH." (PMID 33924243, 2021).
neurological disorders (continued). "The enhancement of Sirt1 activity may be a promising strategy for the prevention and treatment of neuropathic pain and neurological disorders." (PMID 32089065, 2020). "It has been suggested that modulation of mammalian sirtuins like SIRT1 may thus be a right approach in slowing the trajectory of aging-related degenerative changes in the central nervous system and neurologic disorders." (PMID 31747893, 2019). "Whereas the levels of SIRT1 may decrease in situations such as aging or inflammation, evidence has demonstrated that the SIRT1 signaling pathway is activated in various neurological disorders." (PMID 31340436, 2019). "In consideration of the potential binding sites between SIRT1 and miR-448, and their roles in neurological disorders, we hypothesized that they might interact with each other and have an impact on SCII progression." (PMID 29561961, 2018). "Of note, SIRT1 is a class III histone deacetylase that may mediate the protective effects of neurons in neurological diseases such as brain cancer." (PMID 29991742, 2018). "Researchers have established different roles for brain SIRT1 in different neurological diseases." (PMID 30532738, 2018). "Apart from this, SIRT1 has also been found to mediate beneficial effects in neurological diseases." (PMID 30532738, 2018). "The finding of the present study suggests that SIRT1 might be a therapeutic target for certain neurological diseases related to NMDA-mediated excitotoxicity." (PMID 29081884, 2017). "SIRT1 has been reported to play an important role in many neurological diseases." (PMID 28042384, 2016). "Furthermore, we focused on elucidating the specific mechanisms involving SIRT1, Nrf2, NF-κB, Cox-2, and iNOS/NO• molecules upstream and downstream of each other in central neurological disorders, highlighting their connections with ferroptosis and neuroinflammation." (PMID 38671843, 2024). "Therefore, in general, SIRT-1 is important in brain functioning and neurological diseases." (PMID 39061398, 2024). "Our findings discover a key regulatory mechanism for sphingolipid homeostasis and neural differentiation, further imply that pharmacological manipulation of SIRT1-mediated sphingomyelin degradation might be beneficial for treatment of human neurological diseases." (PMID 34042046, 2021). "SIRT1 may function as a key target in neurological diseases." (PMID 29991742, 2018). "Moreover, SIRT1 has been implicated in modulating general cognitive enhancement and synaptic plasticity through the regulation of BDNF during normal brain aging as well as onset of neurologic disorders." (PMID 28706491, 2017). "As plasma levels of SIRT1 were found to be increased in MS patients when compared with non-neurological disease controls, it is also postulated that soluble/circulating SIRT1 is an adaptive response during MS and it may play an important role in disease pathogenesis." (PMID 25159125, 2014). "Importantly, SIRT1 activity is enhanced by small-molecule compounds; therefore, development of small-molecule activators could lead to novel therapies against neurological diseases." (PMID 23888142, 2013). "In this review, we focus on the effects of SIRT1 and SIRT3 on metabolic regulation and their anti-aging activity in brain, and further discuss potential pharmacological approaches to remedy and prevent age-associated neurological disorders by targeting sirtuins." (PMID 23888142, 2013). "Thus, the activity of SIRT1 appears to be regulated by a promoter-dependent change in expression mechanism, which may have an impact on the elderly’s metabolism or the progression of neurological disease." (PMID 38706642, 2023). "The authors concluded that occludin, via NFκB/SIRT-1 pathway, modulates HIV-1 transcription, pointing to a significant role of SIRT1 in the pathogenesis of neurological disorders in HIV-infected patients." (PMID 34685718, 2021).
neurological disorders (continued). "Increasing evidence supports that oxidative stress may be reduced by the activation of Sirtuin1 (Sirt1), an NAD+-dependent protein deacetylase, in neurological diseases." (PMID 34959841, 2021). "In this review, we highlight the regulation of SIRT1 and SIRT2 in various neurological diseases." (PMID 33597872, 2020). "Additionally, resveratrol is known to modulate the activities of AMPK, SIRT1, and PGC-1α, metabolic regulators which have been shown to be involved in the onset of neurological disorders." (PMID 28989978, 2017). "In contrast, other reports also point to the negative impacts of SIRT1 in neurological diseases." (PMID 34650436, 2021).
inflammation (34 papers, 2011 to 2026). Aberrant reaction of the microcirculation characterized by movement of fluid and leukocytes from the blood into extravascular tissues. "The administration of natural β-carotene, in the present study, protected mice against CP-induced ALI and lung inflammation through the activation of the SIRT1 and PPARγ signaling pathway." (PMID 37018237, 2023). "SIRT1 is also implicated in lipid metabolism in the heart, oxidative stress in the heart, protection against HFD-induced cardiac inflammation, and glucose intolerance." (PMID 35897743, 2022). "Regulation of AMPK/SIRT1 activity by catechin is a promising therapeutic strategy against many chronic inflammation and related diseases." (PMID 31100089, 2019). "Thus, PIP alleviates pulmonary inflammation by modulating the SIRT1-mediated inflammatory cascade, inhibits EMT, and activates Nrf2 signaling." (PMID 36499047, 2022). "To verify that the SIRT1–AMPK axis controls allergic inflammation by suppressing mTORC2 activation, we tried to generate knockout mice that were deficient in both AMPK and Rictor in CD4-expressing cells, as Rictor is an important protein involved in the regulation of mTORC2 activity." (PMID 35999454, 2022). "Several studies have demonstrated the importance of SIRT1 in eosinophilic airway inflammation." (PMID 32823491, 2020). "Thus, our results are in line with a recent study that reported melatonin benefits in neonatal rat brain inflammation through an inverse miR-34a-SIRT1 relationship." (PMID 31500354, 2019). "Therefore, SIRT1 is a promising dual-effect target for both synovial hyperplasia and chronic inflammation in RA." (PMID 29784872, 2018). "Sirt1 deficiency but not Ampk deficiency abrogated the geniposide-mediated protection against myocardial inflammation." (PMID 30533173, 2018). "Therefore, APN may renovate intestinal microbiota homeostasis in IBD through SIRT1-AdipoR1/2 signaling pathway, thereby treating intestinal inflammation." (PMID 40713669, 2025). "Therefore, our results suggested that melatonin, an SIRT1 enhancer, may be an effective therapeutic agent to control CS‐induced airway inflammation." (PMID 31762195, 2020). "Moreover, the inhibitory effects of geniposide against myocardial inflammation were completely lost in cardiomyocytes with Sirt1 deficiency, suggesting that Sirt1 but not AMPKα mediated the protection of geniposide against cardiac inflammation." (PMID 30533173, 2018). "Therefore, our results indicate that renal inflammation was induced by increased levels of acetylated-NF-κB (p65) owing to the reduced levels of Sirt1 protein expression, and DR exerted anti-inflammatory effects through the restoration of Sirt1 expression in the kidney of WFRs." (PMID 21949662, 2011). "Chronic obesity-related inflammation activates the HMGB1/TLR4/NF-κB signaling cascade, while concurrent downregulation of SIRT1 further amplifies pro-inflammatory signaling." (PMID 41505418, 2026). "In a CLP septic mouse model, RvD1 promoted the resolution of inflammation by upregulating SIRT1 expression and inhibiting the activation of STAT3, ERK, p38, and NF-κB in lung tissue, thereby reducing the severity of pulmonary inflammation." (PMID 40799817, 2025). "However, the mechanisms of macrophage SIRT1 in airway allergic inflammation remain largely unknown." (PMID 34099590, 2021). "Although monocyte SIRT1 overexpression has been shown to prevent vascular inflammation by improving vascular functions, the precise role of SIRT1 in TLR2-induced vascular inflammation has not been determined." (PMID 31023999, 2019).